EBI3 (Epstein-Barr virus induced 3)
Diseases named in the same sentence as EBI3 in open-access papers (continued):
Sharing a sentence is not in itself a finding about the gene and the disease.
cancer (23 papers, 2012 to 2025). A tumor composed of atypical neoplastic, often pleomorphic cells that invade other tissues. "EBI3 can associate with other cytokine subunits, such as IL-12p35, to form IL-35, which can be produced in humans and mice, mainly by regulatory B and T lymphocytes, and is involved in autoimmunity and cancer." (PMID 32143355, 2020). "It is tempting to speculate that, combined with p28 to form IL-27, expression of EBI3 is maybe linked to immune response in cancer cells." (PMID 22929622, 2012). "Transcription factor EC (TFEC) regulates a variety of cytokines capable of cancer stem cell promotion, while the pro-cancer or anti-cancer role of Epstein-Barr virus-induced gene 3 (EBI3) is less clearly understood." (PMID 38674080, 2024). "To detect the expression level of EBI3 in GC tissues, we used RT-PCR and Western blot to detect the expression levels of EBI3 mRNA and protein in 30 matched cancer tissues and adjacent tissues." (PMID 39291183, 2022). "It was found that the expression levels of EBI3 mRNA and protein in cancer tissues were significantly lower than those in adjacent tissues (P < 0.05)." (PMID 39291183, 2022). "In recent years, studies have found that EBI3 has abnormal expression in a variety of malignant tumors, and the role of EBI3 in different malignant tumors is also different." (PMID 39291183, 2022). "Previous studies in diverse cancer cell lines have shown that EBI3 expression can be induced by TNFα stimulation via NFκB promoter activity." (PMID 31955243, 2020). "To confirm the effect of macrophage-secreted Il35 in cancer metastasis, we used Ebi3−/− mice to conduct the following experiments." (PMID 30218063, 2018). "In the metastatic human cancer samples, mTAMs expressed higher levels of EBI3 and IL12A compared with peripheral blood monocyte-derived macrophages (PMMs)." (PMID 30218063, 2018). "Western Blot results showed that the protein expression of EBI3 was higher in cancer (C) than in normal tissues (N)." (PMID 27682874, 2016). "Finally, to assess the clinical relevance of our findings, we performed a pan-cancer survival analysis of EBI3 and IL12A expression using the TCGA database including solid tumors only." (PMID 40610398, 2025). "Whether the expression of EBI3 predicts a good or poor prognosis for cancer patients remains a subject of debate." (PMID 34603342, 2021). "Although EBI3 is predominantly expressed in placenta among normal tissues, its expression is induced under pathological conditions including infectious diseases, inflammatory diseases, autoimmune diseases, cancers, and so on." (PMID 34603342, 2021). "The interaction between transmembrane EBI3 and octExosomes in the cancer microenvironment is still unknown." (PMID 33723306, 2021). "Further, EBI3 is frequently expressed in a subset of human malignancies, suggesting that EBI3 may play a functional role in cell–cell adhesion during the progression of human cancers." (PMID 33723306, 2021). "Particularly, EBI3+IL-12p35+ and EBI3+IL-27p28+ phenotype TILs were undetectable in this study, although IL-35 production Tregs were observed on inflammatory site, but from human nontumor disease or an IL-35 reporter murine models of human cancer." (PMID 27247488, 2016). "Furthermore, reduction of EBI3 expression by siRNA suppressed cancer cell proliferation and induction of exogenous EBI3 expression conferred growth-promoting activity." (PMID 27867385, 2016). "Therefore, what kind of role EBI3 plays in malignant tumors, whether it can become a new effective therapeutic target for tumors, and whether it can become a breakthrough in overcoming tumors, has gradually attracted people's attention." (PMID 39291183, 2022). "Furthermore, there is emerging evidence that IL-30 itself may perform immunomodulatory functions independent of Ebi3 or other binding partners and that IL-30 production is strongly associated with certain cancers in humans." (PMID 34045653, 2021).
cancer (continued). "While the expression of IL-35 was previously shown in carcinoma cell lines, healthy tissue from liver, lung, kidney, and heart do not express EBI3, and, thus, are unable to form IL-35." (PMID 31955243, 2020). "Early findings point to a role for IL-35 in promoting cancer development; expression of p35, but not p28, was correlated with EBI3 in Hodgkin lymphoma and nasopharengeal carcinoma." (PMID 31681561, 2019). "Importantly, most of these identified genes, such as FLT1, EBI3, LEP and BCL6, are highly involved in angiogenesis and immune modulation in malignant tumor progression." (PMID 22929622, 2012). "EBI3 has revealed growth-promoting activity in lung cancer and in colorectal cancer, by stimulating cell proliferation, via the gp130/STAT3 axis, and by restraining tumor infiltrating granzyme B+ CTLs and IFNγ+ CTLs, thus, allowing the cancer to escape immune surveillance." (PMID 32143355, 2020). "Finally, EBI3 can associate with IL-23p19, to form IL-39, which is secreted by the activated murine B cells that mediate lupus-like diseases in MRL/lpr mice, but a clear demonstration of a functional human counterpart is lacking and, therefore, its possible involvement in cancer remains unclear." (PMID 32143355, 2020).
infectious disease (4 papers, 2013 to 2023). A disorder directly resulting from the presence and activity of a microbial, viral, or parasitic agent in humans. "Even though IL-39 shares IL-23p19 with IL-23 and shares EBi3 with IL-27 and IL-35, their roles in human infectious diseases are unclear." (PMID 37215496, 2023). "Our analysis further delineated peripheral transcripts, including the infectious disease susceptibility gene CISH, encoding cytokine inducible SH2-containing protein, and EBI3, encoding Epstein-Barr virus induced 3, putatively modulated by TNFα signaling." (PMID 24236088, 2013). "Based on our findings, blockade of EBI3 may provide a new therapeutic approach for the treatment of infectious diseases, particularly in patients with defective IL-12 immunity." (PMID 24068935, 2013).
bacterial infection (3 papers, 2012 to 2022). "SMARCD3 and EBI3, two genes over-expressed in bacterial infection, are associated with tuberculosis infection and bacterial burden." (PMID 36543117, 2022). "Collectively, these findings demonstrate that EBI3-deficiency conferred resistance to Lm-Ova infection in the absence of IL12p35, indicative of possible antagonistic function of IL-12p35 and IL-27EBI3 in host defense to the intracellular bacterial infection." (PMID 24068935, 2013).
immune disorders (1 paper, 2022). "EBI3 is also a subunit of anti-inflammatory and immunosuppressive cytokines such as IL-27 and IL-35, which suggest MSCs may play a suppressive role in the onset and progression of immune disorders by secreting EBI3." (PMID 36548354, 2022).
EBI3 also shares sentences with these, for which no sentence is quoted: allergic asthma (3 papers); ulcerative colitis (3); acute myeloid leukemia (2); chronic rhinosinusitis (2); oral cancer (2); pancreatic carcinoma (2); acinic cell carcinoma (1); Alzheimer disease (1); ankylosing spondylitis (1); Anxiety (1); Arthritis (1); cardiomyopathy (1); Chagas cardiomyopathy (1); chronic hepatitis B (1); chronic obstructive pulmonary disease (1); colon adenocarcinoma (1); coronary atherosclerosis (1); dermatitis (1); esophageal carcinoma (1); giant cell carcinoma (1); Graves disease (1); hepatitis B (1); Listeria monocytogenes Infection (1); malaria (1); metastatic tumors (1); mucinous carcinoma (1); multiple sclerosis (1); pneumonia (1); primary biliary cirrhosis (1); pulmonary tuberculosis (1).
A further 3 diseases each share a sentence with EBI3 in 1 paper.